TYR (tyrosinase)
Diseases named in the same sentence as TYR in open-access papers (continued):
Sharing a sentence is not in itself a finding about the gene and the disease.
melanoma (continued). "The inhibitory activity of abalone biomimetic peptides against cellular tyrosinase and melanin content was investigated in a melanoma cell line (B16F10)." (PMID 36834568, 2023). "Products of the tyrosinase reaction (melanin intermediate molecules) can thus exhibit useful selective cytotoxicity for melanoma cells, and provide a rational basis for selective DDS, as well as targeted cytotoxicity." (PMID 36428680, 2022). "Several melanoma antigens (Ags) proposed as targets for immunotherapeutics include tyrosinase, NY-ESO-1, gp-100, and Mart-1, all of which contain both human leukocyte antigen (HLA) class I and class II-restricted epitopes necessary for immune recognition." (PMID 35162988, 2022). "Tyrosine analogs that are the substrates of the melanin-forming enzyme tyrosinase can be some of the best candidates for developing specific melanoma-targeting drugs and therapies." (PMID 35742905, 2022). "The skin-depigmenting effect of MB is correlated with the inhibition of tyrosinase, the rate-limiting enzyme in melanin synthesis, in both melanocytes and melanoma cells." (PMID 36230632, 2022). "Studies have shown that QU increases the tyrosinase activity and synthesis of melanoma cells and normal melanocytes to promote melanogenesis." (PMID 36569347, 2022). "One of the L-dopa analogues, 6-hydroxydopa, was found to be highly potent in terms of selective interaction with tyrosinase and toxicity for melanoma cells." (PMID 36428680, 2022). "Melanogenesis inhibition by SCE was assessed in vitro with B16-F10 melanoma cell models and in silico against melanin regulatory proteins Tyrosinase (TYR) and Melanocortin 1 Receptor (MC1R)." (PMID 36500679, 2022). "By probing tyrosinase expression in the tumor bulk, melanoma cells (TYROSINASE-positive cells) were selected, which demonstrated higher levels of BMAL1 expression and increased frequency of BMAL1-positive cells." (PMID 35562405, 2022). "Previous studies have demonstrated that D. crassirhizoma rhizome (DCR) significantly inhibited melanin production in B16F10 melanoma cells and also inhibited tyrosinase activity." (PMID 35520284, 2022). "A DC-based mRNA vaccine encoding CD40Ligand, CD70, and TLR4 (TriMixDC), and transfected with melanoma associated genes (MAGE, Tyrosinase, gp100-TriMix-MEL) was evaluated in a cohort of advanced melanoma patients." (PMID 36016150, 2022). "Considering that the use of hydroxamate-containing HDAC inhibitors is one of the available options for treating melanomas, one must be cautious about the potential effects of tyrosinase inhibition." (PMID 35204163, 2022). "The results demonstrated that C7R notably decreased α-MSH-induced melanin contents and tyrosinase activity in B16F10 melanoma cells in a dose-dependent manner." (PMID 35919819, 2022). "Tyrosine analogues, which are tyrosinase substrates, are, however, excellent candidates for melanoma-specific targeting therapy." (PMID 36428680, 2022). "Although the experimental effort for vaccination against melanoma using tyrosinase is being investigated, the major clinical effort is currently focused on checkpoint inhibitors." (PMID 35359389, 2022). "In the present study, ITMFAb decreased MITF expression and tyrosinase expression in B16BL6 melanoma cells exposed to α-MSH." (PMID 36422527, 2022). "A previous study showed TYR downregulation and reduced melanin content in vemurafenib-resistant cells consistent with melanoma cell de-differentiation." (PMID 35883549, 2022). "A phase I clinical trial evaluated the use of myeloid DCs activated and loaded with HLA-A*02:01-restricted melanoma peptides gp100 and tyrosinase ex vivo." (PMID 35053435, 2022). "UVB-induced melanogenesis is mediated in part by IL-1β, leading to upregulation of the TYR/TRP1 expression in melanoma B16 cells." (PMID 35572734, 2022).
melanoma (continued). "Based on the results of the cell viability test, melanin content, and activity of tyrosinase, a key melanogenesis enzyme, in SK-Mel-2 human melanoma cells, hydrogen peroxide at 0.1 mM was chosen to induce melanogenesis." (PMID 36296601, 2022). "Tyrosinase, which has a binuclear copper cluster, in the common mushroom (Agaricus bisporus) and human malignant melanoma, is a crucial enzyme in melanogenesis." (PMID 36500294, 2022). "PP60 significantly inhibits the cellular tyrosinase (p < 0.05) and reduces the melanin (p < 0.05) contents of melanoma cells." (PMID 36091602, 2022). "The idea is to conjugate NCX inhibitors with substrates of tyrosinase to make specific anti-melanoma prodrugs that can be released by cleavage ability of tyrosinase and induce cell death of melanoma." (PMID 35055084, 2022). "The use of phenolic melanin precursors appeared more rational and promising for the development of melanogenesis-based anti-melanoma agents because the oxidation of phenolic compounds is only dependent on tyrosinase present in melanocytes and melanoma cells." (PMID 36428680, 2022). "Immunological responses were assessed in 11 patients with stage IV melanoma to intranodal mature DC vaccine pulsed with peptide antigen A (one of tyrosinase, MelanA/MART-1, or MAGE-1) in a normal lymph node." (PMID 35626042, 2022). "We used as a model system a melanoma cell line stably expressing a truncated form of the autoantigen tyrosinase which is decorated with seven N-glycosylation sites, all oligomannose-type glycan structures, sensitive to class I mannosidase processing." (PMID 36699698, 2022). "In α-MSH-stimulated B16BL6 melanoma cells, inhibitions of tyrosinase expression and activity reduced melanin production." (PMID 36422527, 2022). "Phenolic compounds are known to be more selectively toxic to melanoma cells due to the specific activation of phenols by tyrosinase and the systemic effect of catechols by autoxidation." (PMID 36428680, 2022). "In this approach, we specifically focused on the substrate of tyrosinase, which is highly expressed in malignant melanoma." (PMID 36428680, 2022). "In a research study, the efficacy of Panax ginseng leaves extract based AuNPs on tyrosinase activity, tyrosinase gene-expression, and cellular melanin concentration in murine melanoma B16BL6 cell lines was investigated." (PMID 36615414, 2022). "For example, a classic T‐cell epitope (YMDGTMSQV) formed by PTM of tyrosinase specifically occurs in melanoma and alteration in glycosylation patterns seen in melanoma can increase the number of targets for tumour‐specific antibodies." (PMID 35218154, 2022). "Dryopteris crassirhizoma rhizome (DCR) inhibits melanin production in B16F10 melanoma cells and tyrosinase activity." (PMID 35520284, 2022). "We explored some strategies for suppressing melanoma cell metastasis to the lung and brain through modulating tyrosinase activity." (PMID 35265199, 2022). "When C7R was pretreated in B16F10 melanoma cells stimulated by α-melanocyte-stimulating hormone, this compound reduced melanin accumulation and murine tyrosinase activity." (PMID 35919819, 2022). "Our analysis identifies established melanoma risk variants such as disruptive coding alleles of MC1R and TYR." (PMID 35357426, 2022). "For example, a DNA vaccine against human tyrosinase is approved to treat oral malignant melanoma in dogs." (PMID 35303904, 2022). "Melanoma cultures were also stained for fibroblast (vimentin), melanoma (tyrosinase), and dendridic cell (CD11c) markers at day 0 and day 14 by immunohistochemistry." (PMID 35162988, 2022). "Tyrosinase, an enzyme located in melanosomes, is overexpressed in and relatively specific for malignant melanoma." (PMID 35055084, 2022). "Cell-based experiments performed on B16F10 melanoma cells demonstrated that compounds 1b and 1f suppressed melanogenesis more than kojic acid due to their greater inhibitory effects on cellular tyrosinase." (PMID 35242283, 2022).
melanoma (continued). "In a study, 43 patients with advanced melanoma allocated to intradermal (n = 21) and intranodal (n = 22) groups were treated with a DC vaccine pulsed with melanoma antigens gp100 and tyrosinase peptides together with KLH." (PMID 35626042, 2022). "In this study, 0.1 mM hydrogen peroxide was used to induce melanogenesis in SK-Mel-2 human cancer melanoma cells by increasing melanin content and the expression of the melanin-synthesizing gene tyrosinase." (PMID 36296601, 2022). "The study provided substantial evidence that fucoidan inhibited the proliferation and tyrosinase activity of B16 melanoma cells." (PMID 36437391, 2022). "NPrCAP showed a high substrate affinity for tyrosinase and exhibited melanoma-specific and irreversible cytotoxicity." (PMID 36428680, 2022). "A specific enzyme tyrosinase catalyzes the oxidative conversion of L-tyrosine to melanin pigments in melanocytes and malignant melanoma cells." (PMID 36428680, 2022). "Tyrosinase inhibitors have been shown to have antiproliferative effects against melanoma cell lines." (PMID 36415425, 2022). "Previous reports show that, in several melanoma cells, expression of differentiation antigens (Tyrosinase, Melan-A or CSPG4) increased after short-term treatment with BRAFi followed by a decrease at long-term, affecting T cell recognition." (PMID 36726591, 2022). "NaOH lysis and L-dihydroxyphenylalanine (L-DOPA) oxidation method were used to measure melanin content and tyrosinase (TYR) activity, respectively, in melanoma B16 cells." (PMID 35572734, 2022). "The cell lines used in this study were human UM 92.1 and mouse melanoma B16F10 (an in vitro system widely used for assessing tyrosinase activity and melanin production)." (PMID 35936703, 2022). "The effect of PP60 on melanin and tyrosinase was evaluated in A375 melanoma cells and zebrafish embryos." (PMID 36091602, 2022). "In this study, we used FTGML to treat B16F10 melanoma cells, and found a significant inhibition of tyrosinase activity and melanin synthesis." (PMID 35159541, 2022). "In this same study, amongst the pigmented melanoma controls only six of the ten cases were positive for tyrosinase." (PMID 36356074, 2022). "For this, proteins extracted from A375 melanoma cells stably expressing soluble tyrosinase were subjected to overnight Endo H digestion in a 10 K microcon device and the released glycans were further captured by centrifugation and analyzed by HRMS." (PMID 36699698, 2022). "It has a decent inhibitory impact on the cell viability, tyrosinase activity (32.25%), and melanin synthesis (63.52%) of B16-F10 melanoma cells induced by α-MSH." (PMID 36185429, 2022). "One of the most important molecular markers in malignant melanoma is the tyrosinase enzyme; its structure contains carbohydrates (glycoprotein enzyme)." (PMID 35656077, 2022). "Since melanoma cells are highly immunogenic cells that express different TAAs such as Melan A, gp100, and tyrosinase, they are suitable for vaccine testing." (PMID 36232698, 2022). "In B16 melanoma cells, melanin production and the protein levels of tyrosinase were suppressed by reducing MITF expression." (PMID 36422527, 2022). "GILT is required for efficient MHC class II-restricted presentation of melanoma antigens, including tyrosinase and tyrosinase-related protein 1, by both APCs and melanoma cells." (PMID 35565329, 2022). "Recently, tyrosinase has been emphasized as a prodrug-converting enzyme for the treatment of melanoma." (PMID 35055084, 2022). "Tyrosinase is a regulatory enzyme in melanin biosynthesis (melanogenesis) and is expressed in the melanocyte and melanoma cells." (PMID 35656077, 2022). "The nanoformulation was also evaluated for antioxidant activity and assayed for cytocompatibility and anti-tyrosinase activity in melanoma cells." (PMID 35890482, 2022). "Tyrosinase is a key enzyme in melanin biosynthesis, being an important target for melanoma and skin-whitening cosmetics." (PMID 35328756, 2022).
melanoma (continued). "C7R did not cause cytotoxicity in B16F10 melanoma cells, and the pretreatment with C7R suppressed α-MSH induced-melanogenesis and tyrosinase activity in B16F10 melanoma cells." (PMID 35919819, 2022). "Metastatic melanotic melanomas not only can release immunosuppressive intermediates but also tyrosinase and other enzymes secondary to cell damage or death leading to uncontrolled melanogenesis in the tumor environment or at the systemic level." (PMID 35359389, 2022). "A recent study identified tyrosinase as a major target of caffeine action in modulating the proliferation and expression of various immunomodulatory cytokines and chemokines in melanomas." (PMID 34722519, 2021). "Recently, promising clinical response was observed in melanoma patients who failed anti-PD1 treatment by using the of RNA-lipoplex vaccine (targeting four tumor associated antigens (TAA) namely NY-ESO-1, MAGEA3, tyrosinase and TPTE; FixVac)." (PMID 33937323, 2021). "First, in vitro cell studies using human melanoma cells showed that HA/TA-LP promoted the uptake of TA, resulting in the inhibition of tyrosinase activity and melanin production." (PMID 34596008, 2021). "A xenogeneic human tyrosinase DNA vaccine was bioengineered for the treatment of oral malignant melanoma, being recommended after local control has been achieved." (PMID 34940378, 2021). "The cellular melanin content and tyrosinase activity in B16-F10 melanoma cells were analyzed to assess the anti-melanogenic effects of OLM and its different fractions." (PMID 33917957, 2021). "In comparison, inotodiol and lanosterol reportedly increased tyrosinase activities as well as melanin content in B16 melanoma cells." (PMID 33777049, 2021). "Results of human tyrosinase inhibitory activity in A375 human melanoma cells showed that compound (Ph9) and Ph6 exhibited 94.6% and 92.2% inhibitory activity respectively while the positive control kojic acid showed 72.9% inhibition." (PMID 33922836, 2021). "Anti-melanogenic effects of Wongam extracts were verified by TYR inhibition activity and melanin content in melanoma cells." (PMID 34563052, 2021). "Mechanistically, our data show that loss/block of TPC2 results in reduced protein levels of MITF, a major regulator of melanoma progression, but an increased activity of the melanin-generating enzyme tyrosinase." (PMID 33875769, 2021). "According to other researchers, very intensive melanogenesis and overexpression of tyrosinase in melanoma is often connected with defective melanosomes, melanosomal membrane destruction, and leakage of intermediates into the cytoplasm." (PMID 33506271, 2021). "It is well accepted that TYR expression increases during tumorigenesis and represents a specific melanoma-related antigen." (PMID 34199192, 2021). "We found that milk exosomes decreased melanin contents, tyrosinase activity and the expression of melanogenesis-related genes in melanoma cells and melanocytes." (PMID 34831071, 2021). "In vitro cell studies using human A375 melanoma cells show that HA/TA-LP can promote the uptake of TA by targeting delivery with resulting inhibition of tyrosinase activity and melanin production." (PMID 34596008, 2021). "Fatty acids modulate the degradation of tyrosinase, a crucial enzyme involved in melanin biosynthesis in melanocytes and melanoma cells." (PMID 34099789, 2021). "Next, the capacity of these derivatives to inhibit tyrosinase-catalyzed melanogenesis was studied in B16F10 mouse melanoma cells and the mechanisms of inhibition were elucidated." (PMID 33946371, 2021). "The upregulation of IL-1β, IL-2, IL-6, and IL-12 mRNA expression was significant in PBMCs co-cultured with melanoma cells depigmented by both tyrosinase inhibitors, compared to pigmented cells." (PMID 34072104, 2021). "In melanoma cells and melanocytes, milk exosomes showed TYR inhibition and melanin content reduction compared with the negative control." (PMID 34831071, 2021).
melanoma (continued). "In B16F10 melanoma cells, all of these derivatives inhibited tyrosinase and melanogenic activity more potently than kojic acid, a representative tyrosinase inhibitor." (PMID 34443550, 2021). "possesses anti-melanogenic properties in B16F10 melanoma cells and human skin models by inhibiting tyrosinase activity." (PMID 34299326, 2021). "In melanoma cells, Xmrk downregulates the tyrosinase gene, which controls melanin synthesis via MAPK inhibition of the transcription factor, microphthalmia-associated transcription factor (MITF), and suppresses melanocyte differentiation." (PMID 34067095, 2021). "This was superior to the responses of tyrosinase and gp100, revealing the potency of cancer-germline antigens and their potential for use in mRNA vaccines against melanoma." (PMID 34696168, 2021). "This study aimed to investigate the diagnostic and prognostic utility of the conventional pan-melanoma cocktail members (HMB-45, melan-A and tyrosinase), in conjunction with SOX10 and SOX11 immunohistochemical (IHC) expression." (PMID 33801642, 2021). "One well-established genetically engineered mouse model of melanoma expresses BRAFV600E from the endogenous locus in tyrosinase-expressing cells with spatiotemporal control." (PMID 34812139, 2021). "That is, it was reported that H1R antagonist (mepyramine) and H2R antagonists (cimetidine, ranitidine, impromidine) increased TYR activity in cultured human melanoma cells, whereas H2R agonists (dimaprit, nordimaprit) decreased the activity." (PMID 34360837, 2021). "The inhibitory effect of arbutin on TYR expression and melanin synthesis was reversed by capsaicin (Chemical structure 29) in B16 mouse melanoma cells." (PMID 34356362, 2021). "Morin induced melanogenesis to increase melanin biosynthesis and intracellular tyrosinase activity in B16F10 mouse melanoma cells." (PMID 33917985, 2021). "We confirmed that the cultured melanocytes or melanoma cells displayed the tyrosinase or Melan-A protein and mRNA expression." (PMID 34944864, 2021). "Different melanoma TAAs used in melanoma immunotherapy approaches include gp100, MART-1, and three enzymes associated with melanin synthesis, tyrosinase (tyr), tyrosinase related protein-1 and -2 (TRP1 and TRP2)." (PMID 33672349, 2021). "Xenogeneic human tyrosinase plasmid DNA vaccination of dogs with advanced malignant melanoma showed potentially therapeutic activity." (PMID 33156394, 2021). "In this study, we found that JUB, EPA, and FRS exhibited potent anti-melanogenic activity in both B16F10 melanoma cells and zebrafish larvae by inhibiting tyrosinase activity and downregulating the melanin-producing cell signaling pathway." (PMID 34299326, 2021). "By adopting in vivo fluorescent imaging strategy, the elevation of the TYR level (or activity) at the melanoma focus can be localized spatially, thereby lessening the risk of false-positive signals." (PMID 34436092, 2021). "Free fatty acids (FFA) have remarkable regulatory effects on melanogenesis and suppressed tyrosinase activity in cultured B16F10 murine melanoma cells." (PMID 34099789, 2021). "β-lactoglobulin decreases tyrosinase activity in human melanocytes, and k-casein inhibits melanogenesis in mouse B16 melanoma cells." (PMID 34831071, 2021). "Stilbenes downregulate melanogenesis-related proteins, such as tyrosinase, tyrosinase-related protein (TRYP) 1, TRYP2, and microphthalmia-associated transcription factor, in melanoma cells [30, -32]." (PMID 34584041, 2021). "At the highest state where c-AMP induction leads to peak MITF activity, melanoma cells express differentiation target genes (i.e., Tyrosinase and MART1), giving rise to a pigmented phenotype and undergoing terminal differentiation." (PMID 34356645, 2021). "In conclusion, the present results confirm that PA inhibits not only cell-free tyrosinase activity but also intracellular tyrosinase in α-MSH-induced melanoma cells." (PMID 33917915, 2021).